CRP (C-reactive protein)
Diseases named in the same sentence as CRP in open-access papers (continued):
Sharing a sentence is not in itself a finding about the gene and the disease.
type 2 diabetes (continued). "A 53-year-old, SARS-CoV-2 positive, male patient with the risk factor diabetes type 2 was referred with dyspnea, fever and fulminant increase of CRP." (PMID 34408751, 2021). "This study, therefore, aims to assess the correlation between serum PCT, CRP and cardiovascular risk in adults with type 2 diabetes." (PMID 34725609, 2021). "The aim of the current study is to evaluate the relation between hs-CRP and incident cardiovascular events and all-cause mortality in high-risk type 2 diabetes patients." (PMID 34753497, 2021). "Our study showed that higher CRP levels are associated with increased values of most body composition parameters both in women with type 2 diabetes and in healthy controls." (PMID 34769939, 2021). "We aimed to assess the correlation between serum levels of procalcitonin, C-reactive protein and cardiovascular risk in type 2 diabetes." (PMID 34725609, 2021). "It was previously shown that, in a prospective study of at-risk Finnish individuals, higher levels of IPA were associated with lower risk of type 2 diabetes and serum CRP-based low-grade inflammation levels." (PMID 33918080, 2021). "At HNF1A, some common and rare signals have been associated with low-density lipoprotein (LDL) cholesterol, circulating C-reactive protein levels, and risk of monogenic diabetes (maturity-onset diabetes of the young type 3) or multi-factorial T2D29–31." (PMID 33531528, 2021). "Beyond conventional risk factors for type 2 diabetes, inflammatory markers such as fibrinogen, C-reactive protein (CRP), and interleukin-6 (IL-6) are also contributors to the development of type 2 diabetes." (PMID 31690939, 2020). "A meta-analysis reported that increased levels of inflammatory markers such as IL-6 and CRP significantly increase the risk of incident type 2 diabetes." (PMID 31690939, 2020). "In recent years, MR analysis has helped us to identify lots of causal effects, such as body mass index and C-reactive protein increase the risk of type 2 diabetes." (PMID 32266232, 2020). "In summary, we found indications of increased risk of type-2 diabetes and osteoarthritis, and elevated levels of CRP associated with RT exposure." (PMID 30894578, 2019). "Despite having a high accumulation of body fat, MHO individuals display lower levels of C-reactive protein, higher adiponectin concentrations, higher insulin sensitivity, and a lower risk of type 2 diabetes." (PMID 31789604, 2019). "Other studies conducted in a senior population revealed a relationship between elevated levels of IL-6, CRP and diminished cognitive function, as well as an increased risk of type 2 diabetes." (PMID 31151190, 2019). "The majority of these studies showed a positive relationship between C-reactive protein and the risk of developing type 2 diabetes." (PMID 29910771, 2018). "A more recent study in a population with a high prevalence of cardiovascular disease and type II diabetes showed that these ratios were significantly associated with HbA1c, glucose, and CRP." (PMID 30453494, 2018). "The circulating markers of inflammation (e.g., TNF-α and IL-6) and acute-phase reactants (e.g., CRP) are considered strong predictors of the development of type 2 diabetes and the possible associated cardiovascular complications." (PMID 29755566, 2018). "In age and sex adjusted model, EN-RAGE, IL13, IL17, complement 3, IL18, TNFRII, IL1ra and CRP were associated with incident type 2 diabetes." (PMID 28258520, 2017). "Multiple studies have shown that associations of CRP and IL-6 with type 2 diabetes vary by race and ethnicity, sex, and body mass index." (PMID 28753646, 2017). "In multivariate models, IL13 (HR = 0.67), IL17 (HR = 0.76) and CRP (HR = 1.32) remained associated with incident type 2 diabetes." (PMID 28258520, 2017). "Further larger and prospective studies are necessary to confirm these associations and causality between serum hs-CRP level and type 2 diabetes." (PMID 28361994, 2017).
type 2 diabetes (continued). "In fact, we note that CRP gene is located within the chromosome 1q21-q25 and this region has been linked to type 2 diabetes and 2-hour glucose by several linkage studies." (PMID 28801571, 2017). "Elevated CRP and IL-6 concentrations are significantly associated with increased type 2 diabetes risks in populations unselected for hemochromatosis diagnoses." (PMID 28331855, 2017). "The liver-derived C-reactive protein (CRP) is a sensitive and systemic biomarker of inflammation, and has been associated with increased risk of developing type 2 diabetes in populations other than Chinese." (PMID 28178951, 2017). "A number of prospective cohort studies and nested case–control studies have reported that CRP is associated with increased risk of developing type 2 diabetes (T2D)." (PMID 28178951, 2017). "The mechanisms underlying the relationships between elevated serum hs-CRP level and increased prevalence of type 2 diabetes cannot be entirely understood, however, there are several plausible mechanisms." (PMID 28361994, 2017). "C-reactive protein (CRP) is associated with progressive diabetic nephropathy in patients with type-2 diabetes (T2DN)." (PMID 27221338, 2016). "Both type 1 and type 2 diabetes are associated with increased blood concentrations of several inflammatory biomarkers, including C-reactive protein (CRP), interleukin (IL)-2, IL-6 and tumour necrosis factor-alpha (TNF-α)." (PMID 27544079, 2016). "For instance, elevated C-reactive protein previously associated with low well-being is a strong independent predictor of Type 2 diabetes." (PMID 26569542, 2016). "Weight loss leads to CRP decrease, and patients with type 2 diabetes are at increased risk of infection." (PMID 27701463, 2016). "There has been current meta-analysis and appraisal of CRP-related studies further demonstrated that higher levels of CRP are correlated with the increased risk for type 2 diabetes." (PMID 28003714, 2016). "In conclusion, the present study demonstrates that CRP is pathogenic in type-2 diabetes and diabetic renal complication." (PMID 27221338, 2016). "Further adjustment for CRP, the association of MetS and PAD was not substantially decreased in men, although our previous studies proved that CRP was associated with MetS and type 2 diabetes in this rural Chinese population." (PMID 25961739, 2015). "Several prospective cohort studies in patients with type 2 diabetes have demonstrated elevated CVD risk with higher CRP levels, with HRs ranging between 1.4 and 2.6." (PMID 25899452, 2015). "Type-2 diabetes is associated with systemic inflammation and higher C-reactive protein (CRP) levels." (PMID 25994228, 2015). "These included loci where individuals carrying the risk allele for CRP encounter higher lipid levels and risk of type 2 diabetes." (PMID 25768928, 2015). "For instance, the A-allele of the SNP rs4420638 in the APOC1 locus increases serum CRP levels and is associated with a lower risk of type 2 diabetes." (PMID 25768928, 2015). "The effect directions were the same for type 2 diabetes and CRP, implying people carrying the risk allele for type 2 diabetes also have higher CRP values." (PMID 25768928, 2015). "In this study, we found CRP rs2808629 was associated with DR in the Chinese patients with type 2 diabetes." (PMID 25887518, 2015). "Hypersensitivity CRP not only adds prognostic information to the Framingham Risk Score but also links to MetS and the incident of type 2 diabetes." (PMID 26193292, 2015). "CRP has also been shown to be positively associated with incident type 2 diabetes in previous studies." (PMID 25994228, 2015). "Both measures were earlier shown to correlate to levels of CRP; moreover, an increase in CRP levels is a known risk factor for type 2 diabetes." (PMID 25638154, 2015). "The evidence that increased serum PAI-1, interleukin-6 and CRP levels are associated with the development of type 2 diabetes is growing." (PMID 26011530, 2015).
type 2 diabetes (continued). "Further analysis showed that CRP mediated the association between the daily smoking quantity and type 2 diabetes, accounting for 50.77% of the association." (PMID 25105149, 2014). "Our study confirmed the previous findings of associations between smoking, CRP, and type 2 diabetes and further found that the association between smoking and type 2 diabetes was partially mediated by CRP." (PMID 25105149, 2014). "The circulating value of CRP reflects ongoing inflammation and/or tissue damage and is associated with cardiovascular disease, type 2 diabetes, smoking, and a sedentary lifestyle." (PMID 25105149, 2014). "It was showed that elevated concentrations of pro-inflammatory cytokines such as IL-6 and acute phase reactants such as C-reactive protein are in turn independent risk factors for the development of type 2 diabetes and CVD." (PMID 25266321, 2014). "This was a cross-sectional study and a causal relationship between cigarettes, CRP, and type 2 diabetes cannot be concluded." (PMID 25105149, 2014). "We thus aimed to examine the prevalence of and modifiable factors associated with elevated CRP among newly diagnosed Type 2 DM patients included in the nationwide Danish Centre for Strategic Research in Type 2 Diabetes (DD2) cohort study." (PMID 25163828, 2014). "CRP mediated this association between the smoking quantity and type 2 diabetes, accounting for 50.77% of the association." (PMID 25105149, 2014). "The results from our explorative study provide new knowledge about CRP levels and associated factors in newly diagnosed Type 2 diabetes patients as compared with previous cross-sectional studies of the general population or persons with prevalent Type 2 DM." (PMID 25163828, 2014). "This same study, based on the results from 22 cohorts of 40,735 participants, also found that elevated CRP levels were significantly associated with increased risk of type 2 diabetes (RR 1.26, 95% CI 1.16–1.37)." (PMID 24988532, 2014). "The results can be summarized as follows: lower CD4 TRECs were significantly associated with higher past BMI, HbA1c, CRP, or diagnosis with type-2 diabetes or fatty liver." (PMID 24651652, 2014). "The association between the smoking quantity and type 2 diabetes was mediated by CRP, which accounted for 50.77% of the association." (PMID 25105149, 2014). "In this study, people with larger waist circumference had higher blood glucose, triglycerides, LDL cholesterol and us-CRP, supporting the importance of the loss of fat mass to facilitate the treatment of type 2 diabetes." (PMID 24443817, 2014). "Higher CRP levels were also shown to be positively associated with an increased risk of type 2 diabetes." (PMID 25105149, 2014). "Additional studies assessing the long-term risk factors for type 2 diabetes revealed that the levels of CRP, IL-6, IL-8, and TNF-α were higher in diabetic populations than the normal population." (PMID 25132859, 2014). "Type 2 diabetes is believed to be associated with inflammation, as evidenced by high levels of C-reactive proteins (CRP) in patients." (PMID 24861977, 2014). "Several prospective studies have demonstrated that elevated CRP levels were significantly predictive of risk of type 2 diabetes." (PMID 24502834, 2014). "A recent meta-analysis involving 22 cohorts comprising 40,735 subjects and 5,753 cases indicated that elevated CRP levels were significantly associated with an increased risk of type 2 diabetes." (PMID 25105149, 2014). "Various studies have shown that the inflammatory factor CRP level in type 2 diabetics is indicative of cardiovascular risk." (PMID 24804267, 2014). "Scores created from these SNPs would therefore show association with CRP level, BMI and consequently (through BMI) greater risk of type 2 diabetes." (PMID 24204319, 2013). "On bivariate analysis, IL-6, hs-CRP, leptin and γGT were positively associated with increased risk of type 2 diabetes; IL-1β and adiponectin were inversely associated with type 2 diabetes risk." (PMID 23251619, 2012).
type 2 diabetes (continued). "As previously reported in a Finnish population as well as Japanese type 2 diabetic patients and healthy individuals, an association between leptin and CRP was observed in the Taiwanese cohort analyzed in the present study." (PMID 22533665, 2012). "Low-grade chronic inflammation has been associated with diabetes type 2, with hs-CRP playing a central role increasing acute phase response." (PMID 22309488, 2012). "A meta-analysis of 16 prospective cohort studies showed that CRP was associated with an increased risk of type 2 diabetes." (PMID 21804937, 2011). "Despite these limitations, we were able to show associations between procalcitonin and CRP with DCFDs, providing a basis for studying the role of inflammation in delirium and coma in the ICU." (PMID 21366899, 2011). "It is, therefore, unlikely that a high GI diet induces the positive association between CRP and risk of type 2 diabetes by increasing CRP concentrations." (PMID 21804937, 2011). "In this population a positive association between CRP and risk of type 2 diabetes was shown previously." (PMID 21804937, 2011). "Although the association of CRP with increased risk of developing cardiovascular disease has been well documented, previous studies on the association of CRP with incident type 2 diabetes have been less consistent." (PMID 20716378, 2010). "In this study, the association of CRP or GGT with type 2 diabetes diagnosed by either glucose or HbA1c criteria is investigated based on a cross-sectional population-based Chinese study in Qingdao, China." (PMID 21076541, 2010). "CRP is a well described marker of risk for development of both coronary heart disease and type-2 diabetes." (PMID 20178593, 2010). "Low-grade chronic inflammation is reflected by a 2–3-fold increase in the systemic levels of certain cytokines as well as C-reactive protein (CRP), and an association has been confirmed between low-grade systemic inflammation and type-2 diabetes." (PMID 20526368, 2010). "The current study revealed that serum level of hs-CRP ≥ 10 mg/L was associated with a 2.593-fold increase in risk of CAD in type 2 diabetes when compared with hs-CRP level < 10 mg/L." (PMID 17178005, 2006). "Additionally, a large-scale cohort study demonstrated a positive correlation between CRP levels and the risk of developing type 2 diabetes, revealing gender differences." (PMID 40864980, 2025). "A prospective cohort study demonstrated that individuals with high levels of both IL-6 and CRP, along with moderate-to-severe periodontitis and type 2 diabetes, had a 2.3-fold increased risk of major adverse cardiovascular events compared to individuals with none of these risk factors." (PMID 41007869, 2025). "High levels of CRP are linked to an increased risk of cardiovascular disease and type 2 diabetes." (PMID 40002762, 2025). "Another RCT tested the potential effects of canakinumab, an anti-inflammatory drug targeting interleukin-1β proven to prevent cardiovascular events, on fasting plasma glucose, HbA1c, and risk of type 2 diabetes in individuals with prediabetes, previous myocardial infarction, and CRP > 2 mg/L." (PMID 38730445, 2024). "The trial found an increased risk of type 2 diabetes with higher concentrations of CRP and IL-6." (PMID 38730445, 2024). "In addition, in a large-scale study, type 2 diabetes and metabolic risk factors such BMI and C-reactive protein are associated with increased venular tortuosity." (PMID 39661465, 2024). "After additional adjustment for waist circumference (Model 2), the direct associations of sex, age, CRP, systolic blood pressure, type 2 diabetes as well as alcohol intake and red meat consumption with EAT thickness persisted among all participants, while the other associations attenuated." (PMID 38796541, 2024).
type 2 diabetes (continued). "However, like the CVDs, type II diabetes, triglyceride levels, and C-reactive protein levels shared most of their risk variants with MDD, and these variants showed high degrees of concordance (>85% of shared variants in the same direction)." (PMID 37693619, 2024). "A two-sample MR study investigated the genetic associations between type 2 diabetes, glycaemic traits, and CRP using 15 genetic variants associated with CRP, with 6 variants located in the CRP gene, and found a potential causal effect of CRP on risk of type 2 diabetes." (PMID 38730445, 2024). "Wang and colleagues conducted a meta-analysis of prospective studies to determine whether elevated levels of inflammatory markers, specifically IL-6 and CRP, are associated with an increased risk of developing type 2 diabetes." (PMID 39404426, 2024). "Moreover, increased CRP is independently associated with higher vascular and all-cause mortality in individuals with type 2 diabetes." (PMID 38281018, 2024). "However, increased liability to MDD was associated with increased risk of loneliness, smoking, type II diabetes, and levels of C-reactive protein." (PMID 37693619, 2024). "CRP is generated from the liver in response to inflammation and has a positive correlation with visceral fat, which is commonly seen in obese people, and it is a risk factor for cardiovascular events and type 2 diabetes." (PMID 39683396, 2024). "Moreover, an increased serum concentration of CRP was associated with a high incidence of many diseases such as chronic kidney failure, type 2 diabetes, cardiovascular disease, sarcopenia, loss of muscle mass, and strength and poor physical performance." (PMID 37488531, 2023). "In line with this hypothesis, a high rate of patients with type 2 diabetes was associated with elevated serum-CRP levels." (PMID 37107100, 2023). "This suggests that reductions in CRP may also be associated with improvements in other cardiovascular risk factors in people with type 2 diabetes." (PMID 36467859, 2022). "The USP44 gene, harboring the only non-synonymous variant identified in this multi-population GWAS meta-analysis, has been associated with type 2 diabetes, C-reactive protein levels, and acute myeloid leukemia in prior GWAS, but has not been implicated in anthropometric traits in prior studies." (PMID 35653334, 2022). "Previous studies showed the association between Hs-CRP and type 2 diabetes." (PMID 35805792, 2022). "Compared to C-reactive protein, procalcitonin may be a better surrogate marker for cardiovascular risk prediction in this population with type 2 diabetes." (PMID 34725609, 2021). "Elevated CRP levels in type II diabetic patients have been the focus of many studies as it has been shown to be a risk factor for type II diabetes through low-grade inflammation, although the exact pathomechanism remains unknown." (PMID 34063875, 2021). "Our findings revealed that salivary CRP levels increased with increasing serum HbA1C levels, suggesting an association between glycaemic control and systemic inflammation in participants with established type 2 diabetes." (PMID 33676486, 2021). "In addition, the risk of developing type 2 diabetes was highest among subjects with elevated IL-18 and CRP or IL-18 and IL-6, respectively." (PMID 34829612, 2021). "High levels of CRP are considered a risk for heart conditions, type II diabetes, and AMD." (PMID 33604378, 2021). "Hyperlipidemia increases the risk of cardio-cerebrovascular disease in patients with type 2 diabetes, and hyperlipidemia combined with the elevation of hs-CRP may induce higher risk of cardio-cerebrovascular disease in patients with type 2 diabetes." (PMID 29739462, 2018). "Therefore, we prospectively examined the relation between plasma levels of CRP and risk of type 2 diabetes (T2D) among a Chinese population." (PMID 28178951, 2017).